TNF (tumor necrosis factor)
Diseases named in the same sentence as TNF in open-access papers (continued):
Sharing a sentence is not in itself a finding about the gene and the disease.
tumor (continued). "For example, we showed that both TNF and IL1, another proinflammatory cytokine, are potent inducers of COX2 expression in 18Co cells, which could, by stimulating prostaglandin synthesis, further impact the crosstalk between tumor cells and stroma." (PMID 24818101, 2014). "All five sensitive tumor cell lines but not the resistant cell line KNS-62 displayed a clear accumulation of intracellular ceramide after induction of programmed necrosis by TRAIL/zVAD/CHX or TNF/zVAD/CHX." (PMID 24507727, 2014). "In our study however, TNF-α was not secreted by any of the tumor models investigated." (PMID 25401795, 2014). "Pointing to factors independent from RIPK3 that additionally regulate the resistance of tumor cells against programmed necrosis, MKN-28 cells expressed similar levels of RIPK3 as Colo357 or Panc89 cells but were resistant to both TRAIL/zVAD/CHX and TNF/zVAD/CHX." (PMID 24507727, 2014). "In addition, the tumor was converted into an immunostimulatory environment characterized by a Th1 profile in which several cytokines were upregulated, including IL-2, IL-1, IFN-γ and TNF-α." (PMID 23441198, 2013). "We also observed that exogenous TNFα elicited MS formation in MCF7 to a higher extent than in MCF10 cells, a phenomenon that was mimicked by the administration of the supernatant of tumor associated fibroblasts (TAF), but not of normal mammary gland fibroblasts (NAF)." (PMID 23372804, 2013). "Notably, the inhibitory effects of L-NMMA and anti-TNF-α did not completely abolish the tumor cell cytotoxicity suggesting that additional tumoricidal factors are operative in this system." (PMID 23964349, 2013). "On the other hand, high permeability of tumor vasculature as well as high concentration of chemotherapeutic agent 5-FU render gradient concentration distribution of TNF-α in tumor tissue, rather than convective distribution, which aggregates the apoptosis of vascular endothelial cells in the tumor." (PMID 23593411, 2013). "Most importantly, removing egr from TAH's has drastically different consequences on tumors with different genotypes: scrib−/− tumors cannot be eliminated from the tissue without egr+/+ hemocytes, indicating a tumor suppressive role for TAHs and TNF signaling in this genetic context." (PMID 24392358, 2013). "Moreover, TNFα secretion triggered in NK cells upon incubation with tumor target cells or engagement of NKG2D receptor was not impaired in fluvastatin-treated NK cells." (PMID 23667543, 2013). "In viewing TWEAK’s pro-proliferative and apoptosis-blockade activities in HCC, alongside the relative refractoriness of this tumor type to TRAIL-induced apoptosis, we posited that there may be functional cross-talk between these TNF pathways wherein TWEAK signaling contributes to TRAIL-resistance." (PMID 24130833, 2013). "In addition, ex vivo incubation of TAM with exosomes from EGCG-treated 4T1 cells skewed polarized these macrophages away from the tumor-promoting M2- to a tumor-inhibiting M1-like phenotype, as evidenced by down-regulated the expression of IL-6 and TGF-β, but up-regulated TNF-α expression." (PMID 24044575, 2013). "In addition, hyperthermia has been demonstrated to enhance Fas-L, tumor necrosis factor-α (TNF-α) and TNF-related apoptosis-inducing ligand (TRAIL) expression, and to increase tumor cell sensitivity towards their receptors, which ultimately induces apoptosis through the death receptor pathway." (PMID 23946791, 2013). "HGAG did not inhibit TNF-induced migration of the B16F10 tumor cells." (PMID 23437168, 2013). "Importantly, to investigate whether CD4+ and CD8+ T cells infiltrated in RdB/IL23/p35-infected tumor tissues are IFN-γ- and TNF-α-co-expressing T cells, FACS analysis was carried out on lymphocytes isolated from tumor." (PMID 23844018, 2013). "ELISA analysis showed that DRibbles stimulation, similar to LPS, could significantly increase the levels of IL-6, IL-10 and TNF-α, whereas whole tumor cell lysate stimulation could not." (PMID 23326458, 2013).
tumor (continued). "Furthermore, inhibition of TNF-α signaling did not decrease tumor cell killing, thus providing therapeutic selectivity." (PMID 23468959, 2013). "Interestingly, we found that fluvastatin did not inhibit the release of TNFα elicited by NK-tumor cell target interaction or engagement of FcγRIIIA." (PMID 23667543, 2013). "GLA and DGLA could also induce T-regulatory cell activity, e.g., transforming growth factor (TGF)-beta-producing T cells, and reduce proinflammatory interleukin (IL)-1 and tumor necrosis factor (TNF)-alpha production, indicating immunity mechanism is likely to participate in the anti-tumor effect." (PMID 22333072, 2012). "For example, ROS are able to induce pathways, like the TNF-α/NF-κB- and PI3K signaling pathway that are involved in increased hypoxia-inducible factor α (HIFα) expression and that activate genes playing an essential role in angiogenesis and tumor metastasis, thereby contributing to tumor growth." (PMID 23185449, 2012). "TNF-α shedding was significantly inhibited in the infliximab group compared to the vehicle, but surprisingly infliximab did not inhibit tumour growth, in contrast to the published study showing that TNF-α shRNA knockdown did inhibit IGROV1-Luc tumour growth in vivo." (PMID 22792380, 2012). "However, SE and EE tumor-bearing mice showed significant increases in IL-6, TNF-α, MCP-1 and PAI-1 compared to SE and EE non-tumor-bearing mice." (PMID 23272114, 2012). "Recent studies have demonstrated that LLC cells-produced factors such as versican is necessary for tumor growth and metastasis, a process that depends on TLR2-mediated myeloid cell activation, where activation of NF-κB results in inflammatory factors TNFα, IL-6 production." (PMID 23284890, 2012). "Given the observation of PSK and docetaxel-induced TIL enhancement, we further analyzed whether any changes in IFN-γ, IL-2, TNF-α, TGF-β, perforin, granzyme B and FoxP3 mRNA expression in the tumor micro-environment could be observed in response to the treatments." (PMID 22159900, 2012). "These cells were then treated with or without 1) tumor lysate (TL), 2) TL + TNF-α, 3) OK-432." (PMID 23300824, 2012). "To study the effects of pardaxin on tumor functions, we performed a real-time RT-PCR analysis of caspase-3, caspase-7, caspase-8, caspase-9, Bax, Bcl-2, STAT2, ATF3, STAT3, SOCS3, IL-2, cathelicidin, TNF-α, MyD88, NF-κB1, p65, IFN-β1, IFN-γ, IL-1β, IL-6, IL-7r, and IL-10." (PMID 23015777, 2012). "Moreover, conditioned media from TNF-stimulated LNCaP-C4-B2 cells induced in vitro mineralisation of MC3T3-E1 osteoblast-like cells, suggesting that TNF within the tumour microenvironment could play a role in bone remodelling and promote osteoblastic activity." (PMID 23326670, 2012). "Additionally, tumor cells were found to have increased expression of Fas, which might be up-regulated by IFN-γ and TNF-α." (PMID 21311755, 2011). "The efficient stimulation of tumor-specific T lymphocytes by DCs requires the presentation of tumor-derived epitopes on MHC class I and II molecules together with second signals (costimulatory molecules CD80, CD86, CD40) and proinflammatory cytokines such as IL-12 or TNF-α." (PMID 22110524, 2011). "It is suggested that LPS, but not IL-12, induces potent TNF production from Kupffer cells/macrophages, which may induce adverse effects on the host defense, especially in tumor-inoculated mice." (PMID 22190974, 2011). "Therefore, IFN-γ, TNFα and TRAIL of these immune cells may cooperate to effectively induce tumor cell apoptosis when infiltrated into tumor." (PMID 21264227, 2011). "In addition, TNF-α not only acts as an autocrine growth factor but also induces the expression of other growth factors such as amphiregulin, EGFR and TGF-α, leading to increased tumour proliferation." (PMID 20087353, 2010).
tumor (continued). "However, the mechanisms of MA action in inflammation and cancers are still not clear, and the synergistic effects of MA and TNFα in inhibiting tumor growth and proliferation have not been investigated." (PMID 20367887, 2010). "We showed that TNFα and IL-1β also failed to induce c-jun in cells expressing dnTCF4, confirming the importance of Wnt signaling for the biological activity of these cytokines and for the interaction of tumor cells with macrophages." (PMID 20661477, 2010). "Recently, multiple reports indicated that tumor cell death induced by multiple, chemically distinct SMAC mimetics was in fact dependent on the proteasomal degradation of multiple members of the IAP family and subsequent induction of TNFα production and caspase-8 mediated death." (PMID 20067634, 2010). "Furthermore, HO-1-mediated protection against TNF-induced cell death is not restricted to tumour cells, as endothelial cells or human fibroblasts induced to express HO-1 fail to undergo apoptosis." (PMID 21307398, 2010). "Antioxidants block the cytotoxic effect of TNF-α and MnSOD is sufficient for cellular resistance to the cytotoxicity of TNF-α, suggesting that the generation of O2•− in mitochondria may contribute to TNF-α induced tumor cell killing." (PMID 20532186, 2010). "However, in these studies TNF-α has no activity against tumor cell lines in in vitro assays, and exerts no synergy with chemotherapy or radiotherapy in this setting." (PMID 20178622, 2010). "There is therefore debate as to whether or not TNFα plays a role in NSCLC tumour cytotoxicity or conversely, tumour progression." (PMID 20573209, 2010). "Thus synergistic increase in TNFα production upon co-stimulation with IFNγ and antibody-coated tumor cells was not surprising." (PMID 19148288, 2009). "Thus, a severe diminution of TNF-α can delay tumor colonization by S. Typhimurium but does not abolish it." (PMID 19693266, 2009). "To test this hypothesis, we measured the amount of TNFα produced by IFNγ-primed macrophages in response to antibody-coated tumor cells in presence or absence of PtdIns 3-kinase/Akt inhibitor." (PMID 19148288, 2009). "Also, in Experiment II, without tumor implantation, the same patterns of expression were observed for TNF-α and IL-10." (PMID 19040745, 2008). "TNF-α is a non-glycosylated 17 kDa protein that exists as a trimer in solution, has receptors on almost all somatic cells, regulates immune modulation, and is cytotoxic to tumor cells." (PMID 18950540, 2008). "However, if TNF was neutralized in T cells deficient in perforin and IFN-γ significant tumor regression was no longer observed." (PMID 18001476, 2007). "The aim of the study was to assess the effect of metoclopramide on tumour development of NMU-induced tumours in Wistar rats, and at the same time to study acute and chronic administration of (LH-RH analogue) goserelin on PRL, TNFα and NO expression in this experimental model." (PMID 18045456, 2007). "In order to explore whether adipose tissue-derived cytokines and lipid mobilising factor are involved in MAC16-induced lipoatrophy, gene expression of TNFα, IL-6 and zinc-α2-glycoprotein (ZAG) known as a lipid-mobilising factor, in white fat was determined in tumour-bearing and freely fed animals." (PMID 17047651, 2006). "However, DC that had engulfed apoptotic cells caused the release of three fold more TNF-α than non-loaded DC, indicating that CD8 T cell activation had occurred and the release of a molecule that promotes tumor cytolysis was present." (PMID 16029505, 2005). "In vitro, no or only minor sensitivity of tumour cells to TNF-α was found." (PMID 12610519, 2003). "This does not preclude an increase in tumour TNF-α levels, which might only be detected by examining tumour biopsies." (PMID 12698178, 2003).
tumor (continued). "Weekly or three-weekly dosing was well tolerated at doses up to 3700 mg m–2 and, in addition to the DCE-MRI changes, elevated tumour but not serum TNF levels and plasma serotonin metabolite levels were observed, consistent with preclinical data (M Jameson and GJ Rustin, personal communications)." (PMID 12888809, 2003). "This extremely rapid type of cell death is not mediated by the death inducing ligands CD95L, TRAIL and TNF but by perforin and granzyme B. Surprisingly, neither mitochondria nor any of the known caspases appear to be involved in this type of tumour cell killing." (PMID 11875749, 2002). "Phase I trials of DMXAA show evidence of decreased tumour blood flow and increased plasma 5HIAA, but only a small increase in plasma nitrate and no increase in plasma TNF." (PMID 12177785, 2002). "When used alone TNF had no cytotoxic or cytostatic effect on this tumour cell line." (PMID 11953868, 2002). "Several cytokines--interleukin 2 (IL-2), tumour necrosis factor alpha (TNF-alpha) and interferon gamma (IFN-gamma)--and prostaglandin E2 (PGE2) known to modulate tumour growth and metastasis were examined to determine whether they regulate nm23 expression in JAR in vitro." (PMID 8080727, 1994). "In particular, one monoclonal antibody to TNF alpha (MAb 32) has been identified which failed to inhibit binding and cytotoxicity of TNF alpha on WEHI-164 tumour cells but which was a potent inhibitor of TNF alpha-induced endothelial cell procoagulant activity on bovine aortic endothelial cells." (PMID 1377483, 1992). "No TNF was detected in the MAC16 tumour or in the serum of tumour-bearing animals." (PMID 3390373, 1988). "Moreover, by inhibiting pro-inflammatory cytokines like IL-6 and TNF-α in the TME, AE can mitigate chronic, tumor promoting inflammation and modulate the activities of other immune cells, including T cells and dendritic cells, thus establishing a microenvironment detrimental to tumor proliferation." (PMID 41601956, 2026). "Notably, GSDMD knockout did not completely inhibit the production of IL-6, tumor TNF-α, and IL-10, suggesting that GSDMD-independent pathways may contribute to inflammation." (PMID 41345109, 2025). "In the AOM/DSS-induced murine CAC model, Th17-related cytokines, including IL-17A, IL-21, IL-22, TNF-α, and IL-6, are produced by tumor-infiltrating lymphocytes (TIL), which could activate the STAT3/NF-κB pathway, thereby promoting CAC cell proliferation and accelerating tumor progression." (PMID 40109347, 2025). "Notably, we showed that patients with tumors having higher TNF-α and TWEAK tumor secretion capacity in vitro also had correspondingly elevated levels of these cytokines in their perilymph, suggesting that our in vitro system could predict in vivo levels of these hearing loss-associated biomarkers." (PMID 39923035, 2025). "Furthermore, the secretion of pro‐inflammatory cytokines, including IFN‐γ, TNF‐α, and IL‐6, was attenuated in irradiated 4T1 cells co‐culture supernatants relative to non‐irradiated 4T1 cells co‐culture, potentially due to the RT‐induced promotion of TGF‐β secretion by tumor cells." (PMID 40470716, 2025). "A recent study indicated that T-cell effector cytokines IFN-γ and TNF-α induced cytokine and chemokine secretion from NSCLC patient-derived CAFs in vitro, which may affect immune cell recruitment and activation and, ultimately, tumor progression and treatment response." (PMID 40244052, 2025). "Notably, in the DMBA + skimmianine treatment group, the tumor burden appeared reduced in approximately 49% of the animals, as evidenced by partial preservation of the mammary gland architecture, fewer malignant clusters, and attenuated PCNA and TNF-α immunoreactivity (p = 0.191)." (PMID 40430573, 2025).
tumor (continued). "In addition, the tumor-infiltrating CD8+ T cells within the S100a1KD tumors demonstrated enhanced effector activity compared to those in the scramble control, as shown by their ability to secrete interferon-γ (IFN-γ), granzyme B (GZMB) and tumor necrosis factor-α (TNF-α)." (PMID 40090947, 2025). "Notable enrichment in the TNF and NOD-like receptor signaling pathways suggested that the combination might activate non-classical cell death mechanisms such as pyroptosis and necroptosis through multi-target synergy, thereby exacerbating tumor cell damage and enhancing anticancer efficacy." (PMID 41008944, 2025). "The anti-tumor activity was mainly attributed to local stimulation of lymphokine production (IL-12, IFN-γ, and TNF) resulting in T-cell recruitment, proliferation, and orientation towards a Th1 profile, as well as non-specific macrophage activation leading to tumor size reduction." (PMID 40724901, 2025). "Additionally, significant activation of the tumor necrosis factor-alpha (TNF-α)/nuclear factor kappa-light-chain-enhancer of activated B cells (NF-κB) pathway has been observed in patients with favorable HIPEC responses, suggesting a key role in tumor sensitization to subsequent chemotherapy." (PMID 40563606, 2025). "Studies have demonstrated that TANs may promote tumor angiogenesis by inducing sustained release of vascular endothelial growth factor (VEGF) from peripheral endothelial cells or by secreting pro-inflammatory and immunosuppressive factors, such as IL-1β, IL-17, TNF-α, CCL4, MMP-9, CXCL8, and ANG1." (PMID 40563367, 2025). "Furthermore, studies have demonstrated that ultrasound-excited 5-aminolevulinic acid (5-ALA) can inhibit tumor growth, promote the polarization of macrophages in the TME towards the M1 phenotype, and enhance the expression of cytokines interferon-gamma (INF-γ), TNF-α, and IL-10 in the TME." (PMID 40521198, 2025). "DAC/IL-33 and PD-1 mAb strongly synergized to increase tumor-infiltrating immune effector cells (i.e., CD4 T cells, CD8 T cells and eosinophils) and intratumoral expression of effector molecules (i.e., IFN-γ, granzyme B, perforin and TNF-α) which may account for therapeutic efficacy." (PMID 40317004, 2025). "In practical terms, TNF-α might serve as a tumor-focused biomarker—its elevation pointing more toward tumor-driven inflammation rather than, say, infection or benign inflammatory conditions (especially since we excluded patients with active inflammatory diseases in this study design)." (PMID 40299527, 2025). "Moreover, activated NK cells could mediate apoptosis of tumor cells through the expression of transcription factors TBX21 and EOMES, factors that can regulate the high expression of cytokines (e.g., IFN-γ and TNF-α) and exert anti-tumor effects through immunomodulatory effects." (PMID 39076970, 2024). "However, signaling pathways such as TNF, NF-κB and so on are stimulated by exposure of the tumor to radiation or chemotherapy drugs in the tumor microenvironment (TME), leading to resistance of cancer cells to apoptosis, as well as promoting angiogenesis and tumor growth." (PMID 38735014, 2024). "In addition to tumor expression specific molecules, we also observed abnormal release patterns of serum neutrophil lymphocyte ratio (NLR), interleukin (IL)-6, and tumor necrosis factor (TNF)-α during radiotherapy, which may have certain indicative effects on radiotherapy effect." (PMID 38239273, 2024). "Additionally, the reduction in TNF-α production in T cells by bryostatin-1 may be compensated by its ability to increase TNF-α production from macrophages, something that would promote anti-tumor activity within the tumor microenvironment." (PMID 39877358, 2024).